LINC01283 (long independently transcribed non-coding RNA 1283)
Gene: Long non-coding RNA gene on chromosome X (39,401,252 to 39,434,824, reverse strand). Ensembl gene ENSG00000234191.
Diseases named in the same sentence as LINC01283 in open-access papers:
LINC01283 is named in the same sentence as 1 disease in open-access papers, as found by Europe PMC text mining. Sharing a sentence is not in itself a finding about the gene and the disease. The quoted sentences say what the papers report.
COVID-19 (1 paper, 2025). A disease caused by infection with severe acute respiratory syndrome coronavirus 2. "We identified four variants associated with COVID-19 severity with genome-wide significance (rs58027632 in KIF19; rs736962 in HTRA1; rs77927946 in DMBT1; and rs115020813 in LINC01283)." (PMID 40149929, 2025).